GSDMD (gasdermin D)
Diseases named in the same sentence as GSDMD in open-access papers (continued):
Sharing a sentence is not in itself a finding about the gene and the disease.
Sepsis (continued). "In this study, we demonstrated that endothelial GSDMD, not myeloid cell–derived GSDMD, was responsible for endothelial injury–mediated ALI and lethality in endotoxemia and sepsis." (PMID 39927458, 2025). "Disulfiram inhibited pore formation by GSDMD but not other members of the GSDM family and improved the survival of mice with LPS-induced sepsis." (PMID 36755018, 2023). "Pyroptosis plays critical roles in LPS‐induced sepsis, including via canonical and noncanonical pathways, toll‐like receptor 4 (TLR4)‐dependent and TLR4‐independent pathways, Gasdermin D (GSDMD) and beyond‐GSDMD‐mediated pathways." (PMID 35593197, 2022).
gastric cancer (74 papers, 2019 to 2025). A primary or metastatic malignant neoplasm involving the stomach. "In gastric cancer (GC), the activation of pyroptosis-related genes (PRGs) such as GSDMD and GSDME is linked to favorable prognosis, while agents like famotidine, simvastatin, icariin, and diosbulbin-B trigger NLRP3 or caspase-3-mediated pyroptosis." (PMID 40806716, 2025). "Pyroptosis is also associated with gastric cancer via downregulation of GSDMD accelerating expression of cdk2/cyclin A2 complexes that promote transition from S to G2 phase, thus accelerating gastric cancer cellular proliferation." (PMID 38645692, 2024). "Studies have demonstrated that GSDMD is dysregulated in gastric cancer and lung cancer, and is associated with tumor proliferation, metastasis, and immune microenvironment." (PMID 37950289, 2023). "Gao and coworkers found that GSDMD is highly expressed in non-small cell lung cancer compared to matched adjacent tumor specimens and is associated with a poor prognosis, whereas low-level expression of GSDMD in gastric cancer promotes tumor proliferation and occurrence." (PMID 37371484, 2023). "For example, GSDMA, GSDMC, and GSDMD are underexpressed in esophageal and gastric cancers, while GSDMB is overexpressed and acts as an oncogene in these cancers." (PMID 40691738, 2025). "In gastric cancer studies, a decreased GSDMD expression has been observed, potentially promoting the proliferation of gastric cancer cells." (PMID 40026444, 2025). "In contrast, GSDMD expression is lower in gastric cancer cells and tissues, where reduced levels of GSDMD promote tumor cell proliferation by accelerating the S/G2 phase transition of the cell cycle." (PMID 40141358, 2025). "In gastric cancer (GC), transcriptional activation of GSDMD by HIC1 induces pyroptosis, releasing inflammatory cytokines to recruit CD8+ T cells, while combinatorial HIC1 overexpression with PD-L1 antibodies synergistically suppresses tumor growth." (PMID 41235238, 2025). "For instance, in gastric cancer, gasdermin D (GSDMD) expression is markedly decreased, thus promoting tumor proliferation." (PMID 41291696, 2025). "Subsequently, we performed IHC staining and observed the downregulation of GSDMD in 97 gastric cancer tissues." (PMID 40279559, 2025). "In gastric cancer, GSDMD expression decreases, markedly promoting the proliferation of tumours and accelerating S/G2 transition by activating extracellular signal-regulated kinase and regulating cell cycle-related proteins." (PMID 39616223, 2024). "For example, quercetin induces pyroptosis in gastric cancer cells by increasing the expression of pyroptosis markers such as GSDMD, GSDME, and NLRP3 in a concentration-dependent manner." (PMID 39584140, 2024). "In gastric cancer, kaempferol, like baicalin, activates the NF-κB pathway, thereby upregulating the expression of caspase-1, GSDMD, and IL-18." (PMID 39584140, 2024). "GSDMD, of which the expression was decreased in gastric cancer (GC) cells compared with adjacent normal cells, acts as a tumor suppressor." (PMID 38221934, 2024). "To elucidate the underlying mechanism of how ALKBH4 inhibits pyroptosis in gastric cancer cells, we evaluated the impact of ALKBH4 expression on key targets (GSDME, GSDMD, NLRP3, Caspase 1) of the pyroptosis pathway using qPCR and western blot experiments." (PMID 38902235, 2024). "Studies have confirmed that GSDMD expression is significantly decreased in gastric cancer cells compared to that in normal cells, resulting in the proliferation of cancer cells." (PMID 38016064, 2023). "Reduced expression of GSDMD was identified as a factor contributing to the progression of gastric cancer by facilitating the transition from the S phase to the G2/M phase." (PMID 38066523, 2023). "in gastric cancer, wherein GSDMD is downregulated among different gastric cancer cell lines by inhibiting the cyclinA2/CDK2 complex and arresting into the S/G2 phase transition." (PMID 37819510, 2023).
gastric cancer (continued). "On the contrary, GSDMD is downregulated in gastric cancer cell lines and tissues, in which diminished GSDMD expression levels lead to promoted tumor cell proliferation through accelerating S/G2 cell transition." (PMID 36932407, 2023). "A recent study has identified lower expression of GSDMD in gastric cancer tissue, which correlated with increased cell proliferation in gastric cancer." (PMID 37664463, 2023). "Increasing DDP-sensitivity in gastric cancer by inducing pyroptosis via regulating the caspase-1/GSDMD pathway." (PMID 38239395, 2023). "GSDMD protects against gastric cancer development by inhibiting the S/G2 cell cycle and abnormal activation of the oncogenic signaling pathway." (PMID 36967609, 2023). "For example, in gastric cancer, the expression of GSDMD is reduced, which promotes the growth and proliferation of tumors." (PMID 37483501, 2023). "In gastric cancer (GC), pyroptosis can be inhibited by the downregulation of gasdermin D (GSDMD), which expedites the expression of Cdk2/cyclin A2 complexes." (PMID 37198617, 2023). "In contrast, GSDMD was found to be downregulated in gastric cancer compared to that in adjacent normal tissue." (PMID 38066523, 2023). "In gastric cancer (GC), the low expression of pyroptosis-affecting protein, GSDMD, is one of the reasons for promoting the proliferation of cancer cells." (PMID 35359956, 2022). "It was confirmed that Cyclin A2 and cyclin-dependent kinase dysregulated GSDMD through the inhibition of PI3K–AKT pathway in gastric cancer." (PMID 35154117, 2022). "A previous study found that, in gastric cancer cells, downregulation of gasdermin D (GSDMD) inhibits pyroptosis and accelerates the expression of Cdk2/cyclin A2 complexes that accelerate GC cell proliferation." (PMID 35562678, 2022). "It has been shown that down-regulation of GSDMD can significantly promote the proliferation of gastric cancer in vitro and in vivo." (PMID 35712482, 2022). "More specifically, the expression of GSDMD (an executor of pyroptosis) is significantly reduced in gastric cancer and promotes tumor proliferation, while in non-small cell lung cancer, GSDMD is highly expressed with a poorer prognosis." (PMID 35741587, 2022). "Our results were similar to a previous study reporting that the expression of GSDMD was reduced in gastric cancer tissues, and the reduction in GSDMD expression significantly promoted tumor proliferation in vivo and in vitro." (PMID 35311148, 2022). "Downregulation of the expression of inflammasomes mediating pyroptosis led to the cell proliferation, while downregulation of GSDMD significantly facilitated the cell proliferation of gastric cancer." (PMID 35571569, 2022). "For example, the expression of pyroptotic inflammasome GSDMD is decreased in gastric cancer (GC) cells, which promotes the proliferation of GC cells." (PMID 36601599, 2022). "GSDMD regulates cell cycle-related proteins in gastric cancer through a series of pathways to accelerate S/G2 cell transformation." (PMID 35311148, 2022). "The expression of caspase-activated GSDMD is beneficial for inhibiting the proliferation of gastric cancer cells." (PMID 35411030, 2022). "Preliminary evidence shows that GSDMD is downregulated in gastric cancer cell lines compared with adjacent normal tissue." (PMID 34522213, 2021). "Conversely, GSDMD reportedly attenuates the transition from the S to G2/M phases of the cell cycle, which results in cell cycle arrest in the gastric cancer cell line BGC823 through the downregulation of cyclinA2 and CDK2." (PMID 34522213, 2021). "Regarding pyroptosis-related mediators, GSDMD expression was found to be decreased in gastric cancer, while GSDME expression is low in gastric and skin cancer." (PMID 33467668, 2021). "Most important, both NLRP3 and GSDMD expression were increased in gastric cancer tissue of patients with H. pylori infectious." (PMID 34266494, 2021).
gastric cancer (continued). "GSDMD was also involved in inducing the release of inflammatory factors such as IL-1β and IL-18, which can promote the growth of gastric cancer cells and accelerate the formation of gastric tumors through immunosuppression." (PMID 34384029, 2021). "We first detected the full length and N‐terminal of GSDMD by immunoblotting to further explore the potential mechanism of BIX combined Cis induced gastric cancer cells pyroptosis." (PMID 32437063, 2020). "GSDMD downregulation contributes to the occurrence and proliferation of gastric cancer, whereas in non-small-cell lung cancer, its upregulation is correlated with poor prognosis." (PMID 32958051, 2020). "They found that GSDMD was down-regulated in gastric cancer and contributed to the occurrence and proliferation of this kind of cancer." (PMID 31616642, 2019). "AIM2 and GSDMD are overexpressed in non-squamous non-small-cell lung cancer, while GSDMD downregulation is associated with gastric cancer." (PMID 38473997, 2024). "Similarly, other previous studies revealed that GSDMD expression was significantly downregulated in other types of cancer such as gastric cancer and colorectal cancer." (PMID 36763290, 2023). "In gastric cancer, downregulated GSDMD promotes tumor growth." (PMID 36932407, 2023). "Suppression of GSDMD expression in gastric cancer can activate the signal transducer and activator of transcription 3 (STAT3) and phosphatidylinositol 3 kinase/protein kinase B (PI3K/PKB) signaling pathways and regulate cell cycle-related proteins to accelerate the S/G2 phase cell transition." (PMID 35990696, 2022). "For example, the expression of the GSDMD could suppress gastric cancer cell proliferation, while low expression of the GSDMD shows a suppressive effect on NSCLC cell proliferation." (PMID 36437960, 2022). "This disagreement may be due to forced GSDMD overexpression, which can reverse gastric cancer cell proliferation by inactivating the ERK, STAT3, and PI3K/AKT pathways, and then inhibiting the Cyclin A2/CDK-2 complex to arrest the S/G2 phase transition." (PMID 36120543, 2022). "However, it has also been proved that down-regulation of GSDMD promotes gastric cancer proliferation by regulating cell cycle-related proteins and over-expression of GSDMC is a prognostic factor for predicting a poor outcome in lung adenocarcinoma." (PMID 36138348, 2022). "Also, some individual pyroptosis genes have been studied, such as NOD2 in colorectal cancer, gasdermin B (GSDMB) in digestive system, and Gasdermin D (GSDMD) in gastric cancer." (PMID 36249755, 2022). "In gastric cancer cells, increased GSDMD inhibits tumor development through cell cycle arrest." (PMID 35345489, 2022). "Studies have found that downregulating the expression of GSDMD could promote the development of gastric cancer." (PMID 34381721, 2021). "In gastric cancer tissues, the expression of GSDMD was lower than normal." (PMID 34381721, 2021). "Therefore, GSDMD has certain clinical significance in the targeted therapy and diagnosis of gastric cancer." (PMID 34381721, 2021). "Pyroptosis-inducing molecule gasdermin D (GSDMD) may be a promoter of gastric cancer cell proliferation, which has been proven both in in vitro and in vivo studies." (PMID 34959621, 2021). "Alternatively, GSDMD expression was significantly downregulated in gastric cancer tissues, which may contribute to the development of gastric cancer through the regulation of cell cycle transition." (PMID 34899864, 2021). "Conversely, the downregulation of GSDMD in gastric cancer (GC) has been found to significantly promote tumor proliferation by accelerating S/G2 cell transition." (PMID 38002346, 2023). "The average expression level of GSDMD in gastric cancer (GC) tissues was lower than that in normal tissues." (PMID 35464869, 2022).
gastric cancer (continued). "Intriguingly, in gastric cancer cells, the expression of GSDMD is downregulated according to a previously published article, which results in abnormal proliferation of cancer cells, indicating that elevating the expression of GSDMD might inhibit the progression of gastric cancer." (PMID 35198448, 2022). "In gastric cancer (GC), GSDMD expression was markedly decreased and resulted in enhanced tumor proliferation both in vitro and in vivo, possibly by accelerating S/G2 cell transition." (PMID 34429144, 2021). "In gastric cancer, RBPMS2 is overexpressed, predicts poor prognosis, and promotes proliferation, invasion, and migration by suppressing NLRP3/caspase-1/GSDMD-mediated pyroptosis." (PMID 41562091, 2025). "GSDMD reduces the expression of Cyclin A2 and Cyclin-Dependent Kinase (CDK2) by inhibiting ERK1/2, STAT3, and PI3K/Akt in gastric cancer (GC) cells." (PMID 35963853, 2022). "Chrysophanol has been shown to promote MKN28 gastric cancer cell pyroptosis via NLRP3/Caspase1/GSDMD, and the Caspase1 inhibitor VX765 can reduce the chrysophanol-induced pyroptosis of MKN28 gastric cancer cells." (PMID 36105214, 2022). "Primary esophageal squamous cell carcinoma and gastric cancer cells showed low expression of GSDMA, GSDMC, and GSDMD, also, GSDME expression was ameliorated in breast, gastric, and colorectal cancers." (PMID 36120543, 2022). "Mechanistically, GSDMD inhibited extracellular signal-regulated kinase (ERK), STAT3, and phosphatidylinositol 3 kinase/protein kinase B (PI3K/AKT) signaling pathways in gastric cancer." (PMID 31616642, 2019). "This cascade ultimately cleaves gasdermin D (GSDMD), inducing pyroptosis in gastric cancer cells." (PMID 40721578, 2025). "Moreover, we administered dimethyl fumarate (DMF), a pyroptosis inhibitor for GSDME/GSDMD, to the cells and noted a reduction in cell mortality, indicating that ALKBH4 mediates the sensitivity of gastric cancer cells to 5-FU through GSDME." (PMID 38902235, 2024). "It has been proved that the down-regulation of GSDMD could promote cell cycle arrest and activate ERK/STAT3/PI3K/AKT pathway in gastric cancer." (PMID 36349258, 2022). "The expression of GSDMD in gastric cancer cells is lower than that in non-cancer cells, and the low expression of GSDMD promotes the proliferation of gastric cancer cells." (PMID 35571063, 2022). "For instance, upregulation of GSDMD in lung cancer or GSDMC in colorectal cancer correlates with poor prognosis and therapeutic resistance, whereas reactivation of GSDME in breast cancer or AIM2 in gastric cancer has been shown to re-sensitize tumors to chemotherapy and inhibit proliferation." (PMID 41291696, 2025). "Additionally, recent studies have indicated that GSDME, rather than GSDMD, can switch chemotherapy-induced caspase-3-dependent cell apoptosis to pyroptotic cell death in gastric cancer cells." (PMID 38016064, 2023). "However, another study showed that the expression of GSDMD in gastric cancer (GC) was decreased compared to that in matched adjacent non-cancerous tissues and that the downregulation of GSDMD accelerated S/G2 cell transition, suggesting that GSDMD may serve as a tumor suppressor." (PMID 34298833, 2021). "Furthermore, the cleavage of GSDME but not GSDMD was observed in the BIX + Cis combined treated group and the KO of GSDME significantly switched pyroptosis to apoptosis, which confirmed that BIX combined Cis induced pyroptosis in gastric cancer dependent on the cleavage of GSDME and caspase‐3." (PMID 32437063, 2020).
colitis (55 papers, 2020 to 2026). Inflammation of the colon. "Dysregulation in microbiome, particularly commensal Escherichia coli, caused GSDMD activation to exacerbate colitis development by boosting IL-18 release from colon." (PMID 39253076, 2024). "Among them, the NLRP3 pathway has been shown to activate GSDMD in a mouse model of colitis-associated colon cancer and mediate the release of IL-1β and IL-18." (PMID 38898209, 2024). "Of note, GSDMD deficiency attenuated the colitis severity induced by DSS compared to that with WT control mice." (PMID 38607004, 2024). "A high-fat/high-sugar maternal diet elevated offspring susceptibility to TNBS-induced colitis by increasing Bacteroidetes, thereby promoting gasdermin D (GSDMD)-mediated pyroptosis and IL-1β production in macrophages." (PMID 39767816, 2024). "Herein, we report that VAD mice exhibited severe DSS-induced colitis associated with increased caspase-11 and GSDMD in the colonic LP, similar to that noted in patients with IBD." (PMID 37240022, 2023). "It has been reported that GSDMD are produced by gut mucosa intestinal epithelial cells (IECs) in colitis model mice, and a deficiency of GSDMD effectively reduced the severity of dextran sodium sulfate (DSS)-induced colitis." (PMID 37580819, 2023). "Accordingly, the administration of cGAS inhibitor RU.521 reduced weight loss, colon shortening, DAI score and histopathological findings in wild type murine models of DSS-induced colitis, totally rescuing the colitogenic phenotype in GSDMD-deficient mice." (PMID 37566032, 2023). "GSDMD deficiency-induced inflammation in macrophages that aggravated experimental colitis by boosting cyclic GMP-AMP synthase (cGAS)-dependent inflammation." (PMID 35677444, 2022). "Here, our data found that GSDMD deficiency protected mice from DSS-induced colitis, which is consistent with a very recent report." (PMID 34721422, 2021). "Additionally, there is evidence that Schisandrin B reduces Colonic tissue pro-Caspase-1 and expression and Gasdermin D protein levels by regulating pyroptosis, which in turn alleviates the loss of epithelial cells in colitis." (PMID 40582769, 2025). "However, in colitis, GSDMD in colonic macrophages mitigates epithelial damage caused by invasive intestinal pathogens via the cGAS signaling pathway, highlighting its protective role in immune defense." (PMID 39994107, 2025). "GSDMD deficiency in mice has been shown to exacerbate chemically-induced colitis." (PMID 39050748, 2024). "Moreover, GSDMD-deficient mice developed substantially less severe DSS-induced colitis than healthy controls." (PMID 37240022, 2023). "Furthermore, a recent study demonstrated that the exacerbation of experimental colitis following the deficiency of pyroptosis executioner Gasdermin D (GSDMD) depends on the hyperactivation of cGAS-STING pathway." (PMID 37566032, 2023). "In contrast, the severity of colitis was attenuated in mice deficient in GSDMD." (PMID 35677444, 2022). "GSDMD plays a dual role in colitis: it can exacerbate intestinal cell inflammatory damage, increasing pathological manifestations, or regulate immune cell-mediated inflammatory responses to reduce the occurrence of colitis." (PMID 39994107, 2025). "For example, in acute myocardial infarction (MI), GSDMD exacerbates inflammatory damage by modulating autophagy in neutrophils, whereas in experimental colitis, it enhances mucosal integrity to counter bacterial invasion, providing protective effects." (PMID 39994107, 2025). "Collectively, these findings indicate that NDGA ameliorates colitis development by inhibiting GSDMD/NR4A1/NLRP3-dependent inflammatory macrophage activation." (PMID 40596758, 2025). "Administration of NDGA alleviated experimental colitis by downregulating the GSDMD/NR4A1/NLRP3 axis-mediated macrophage pyroptosis." (PMID 40596758, 2025). "Neutrophils in the colons of mice with colitis expressed high levels of GSDMD, which were reduced following treatment with Bf‐OMVs and miR‐5119." (PMID 40558568, 2025).